KLHL3 (kelch like family member 3)
Description:
Substrate-specific adapter of a BCR (BTB-CUL3-RBX1) E3 ubiquitin ligase complex that acts as a regulator of ion transport in the distal nephron. The BCR(KLHL3) complex acts by mediating ubiquitination and degradation of WNK1 and WNK4, two activators of Na-Cl cotransporter SLC12A3/NCC in distal convoluted tubule cells of kidney, thereby regulating NaCl reabsorption. The BCR(KLHL3) complex also mediates ubiquitination and degradation of WNK3. The BCR(KLHL3) complex also mediates ubiquitination of CLDN8, a tight-junction protein required for paracellular chloride transport in the kidney, leading to its degradation (By similarity).
Synonyms: KIAA1129; PHA2D
Tractability: Small molecule: it belongs to a druggable protein family. PROTAC: its protein half-life has been measured.
Gene: Protein-coding gene on chromosome 5 (137,617,500 to 137,736,221, reverse strand). Ensembl gene ENSG00000146021.
Subcellular location: Cytoplasm, cytosol; Cytoplasm, cytoskeleton
Pathways (Reactome):
Immune System: Antigen processing: Ubiquitination & Proteasome degradation
Metabolism of proteins: Neddylation
Gene Ontology:
Molecular function: cullin family protein binding; protein binding; ubiquitin-like ligase-substrate adaptor activity; structural molecule activity
Biological process: distal tubule morphogenesis; monoatomic ion homeostasis; proteasome-mediated ubiquitin-dependent protein catabolic process; protein K48-linked ubiquitination; protein ubiquitination; renal sodium ion absorption; ubiquitin-dependent protein catabolic process; macroautophagy; gene expression; potassium ion homeostasis; protein catabolic process; protein polyubiquitination; renal absorption
Cellular component: Cul3-RING ubiquitin ligase complex; cytosol; cytoplasm; cytoskeleton
Genetic constraint (gnomAD): Loss-of-function variants: 15 observed, 61.3 expected, observed/expected ratio (o/e) 0.24, 90% interval 0.16 to 0.38. The upper end of that interval is the gene's LOEUF score, 0.38, which puts it in group 1 of 6, group 1 being the genes least tolerant of losing a copy. Missense variants: 471 observed, 736.71 expected, observed/expected ratio (o/e) 0.64, 90% interval 0.59 to 0.69. Synonymous variants: 236 observed, 279.78 expected, observed/expected ratio (o/e) 0.84, 90% interval 0.76 to 0.94.
Homologues: Orthologues: guinea pig KLHL3 (99% identical), chimpanzee KLHL3 (99% identical), pig KLHL3 (98% identical), rabbit KLHL3 (98% identical), rat Klhl3 (98% identical), mouse Klhl3 (98% identical), macaque KLHL3 (97% identical), dog KLHL3 (86% identical), zebrafish klhl3 (79% identical). Paralogues in human: KLHL2 (77% identical), KLHL17 (47% identical), KLHL20 (44% identical), KLHL5 (40% identical), KLHL12 (39% identical), KLHL1 (39% identical), KLHL4 (38% identical), KLHL8 (37% identical), KEAP1 (37% identical), KLHL28 (36% identical), KLHL18 (35% identical), KLHL10 (33% identical), and 42 more.
Diseases named in the same sentence as KLHL3 in open-access papers:
KLHL3 is named in the same sentence as 34 diseases in open-access papers, as found by Europe PMC text mining. Sharing a sentence is not in itself a finding about the gene and the disease. The quoted sentences say what the papers report.
Hypertension (24 papers, 2013 to 2025). The presence of chronic increased pressure in the systemic arterial system. "Mutations in WNK1, WNK4, CUL3, and/or KLHL3 in humans result in Gordon’s syndrome, a form of hypertension that is heritable and associated with salt-sensitive hypertension, hyperkalemia, metabolic acidosis, and thiazide sensitivity." (PMID 37779139, 2023). "Fluorescence polarisation and structural modelling experiments revealed that its phosphorylation would abrogate the KLHL3 interaction similarly to hypertension-causing mutations." (PMID 35179207, 2022). "Mutations in the gene for KLHL3 are known to cause a variety of metabolic diseases in humans, including a form of high blood pressure called Gordon’s hypertension syndrome, but the protein’s role in human obesity has not been studied." (PMID 36028759, 2022). "In humans, WNK1, WNK4, CUL3, and/or KLHL3 mutations manifest as Gordon’s syndrome, a heritable form of hypertension associated with salt-sensitive hypertension, hyperkalemia, metabolic acidosis, and thiazide sensitivity." (PMID 36028759, 2022). "The present study provides further insights into how Kelch-like adaptor proteins recognize their substrates and provides a structural basis for how mutations in WNK4 and KLHL3 lead to hypertension." (PMID 24641320, 2014). "Mutations in KLHL3 have been identified in patients with inherited hypertension disorders, and several of the disease-associated mutations are located in the presumed Cul3 binding region." (PMID 23573258, 2013). "Variants in CUL3 are often associated with growth impairment in addition to hypertension and electrolyte imbalances and are commonly manifested in infants and children, while variants in KLHL3 and WNKs are associated with hypertension and electrolyte imbalances in mostly adult FHHt patients." (PMID 37845702, 2023). "Since hypertension is an important risk factor for aneurysm rupture, abnormal expression of KLHL3 may be associated with the onset and rupture of IAs." (PMID 32084215, 2020). "Mutations of KLHL3 have previously been linked with hypertension and metabolic acidosis suggesting that these novel SNP associations and deletions may prime individuals to have a greater risk for severe malarial acidosis (hyperlactataemia)." (PMID 29381699, 2018). "KLHL2 is best known for its high expression in the brain, whereas KLHL3 may play a dominant role in the kidney, consistent with the effects of KLHL3 mutations in hypertension." (PMID 24641320, 2014). "Thus, patients with heterozygous CUL3 pathogenic variants are more likely to develop severe hyperkalemia, metabolic acidosis, hypertension, and growth impairment at an early stage than individuals carrying recessive KLHL3, dominant KLHL3, WNK4, or WNK1 pathogenic variants." (PMID 37895227, 2023). "KLHL3 can increase the severity of COVID-19 through its effects on metabolism and the development of comorbidities such as hypertension and obesity." (PMID 41009536, 2025). "The identification of disease-associated variants in both CUL3 and KLHL3 in PHAII patients highlights the important role of the CUL3-KLHL3 complex in the pathophysiology of electrolyte imbalance and hypertension." (PMID 37845702, 2023). "Mutations in KLHL3 and CUL3 have been implicated in PHA II and appear to cause hypertension and electrolyte disbalance." (PMID 35197862, 2022). "PHA II causing mutations in KLHL3 decreases Wnk4 binding to Cul3-RING ubiquitin ligase, decreasing WNK4 degradation and increasing its levels resulting in hypertension." (PMID 35197862, 2022). "CCCs are also involved in hypothalamic signaling in hypertension and the mutations in the regulatory CUL3/KLHL3-WNK-SPAK/OSR1 pathway contribute to the pathology of FHHt." (PMID 33066544, 2020). "Mutations in WNK1, WNK4, KLHL3, and CUL3 all result in the accumulation of WNK-kinase 4 and subsequent hypertension, hyperkalaemia, and metabolic acidosis." (PMID 31795491, 2019).
Hypertension (continued). "This strategy was successfully applied to find new genetic variants for Mendelian CVDs such as hypertension (KCNJ5, KLHL3 gene), dilated cardiomyopathy (BAG gene), or familial combined hypolipidemia (ANGPTL3 gene)." (PMID 29445720, 2017). "In db/db diabetes mouse, PKC phosphorylates KLHL3 on Ser433 and results in WNK4 accumulation, accelerating hypertension in T1DM." (PMID 37006236, 2023). "Mutations in KLHL3 or WNK4 discovered in FHHt patients disrupt the interaction between KLHL3 and WNK4, leading to insufficient degradation of WNK4 and, ultimately, hypertension." (PMID 35327608, 2022). "Interestingly, although FHHt patients with mutations in CUL3, KLHL3 or WNK present the same clinical symptoms, those with mutations in CUL3 have a more severe phenotype, evident in terms of both an earlier age-of-onset and the degree of hypertension and electrolyte disturbance reported." (PMID 27815594, 2017). "Pseudohypoaldosteronism type II (PHAII) is a hereditary hypertensive disease caused by mutations in four different genes: with-no-lysine kinases (WNK) 1 and 4, Kelch-like family member 3 (KLHL3), and cullin 3 (Cul3)." (PMID 26490675, 2015).
pseudohypoaldosteronism type 2 (11 papers, 2013 to 2025). A rare inherited form of hypertension characterized by hyperkalemia, hyperchloremic metabolic acidosis, normal or elevated aldosterone, low renin, and normal renal function. "Mutations in the KLHL3 gene cause pseudohypoaldosteronism type II in either an autosomal dominant or a recessive inheritance pattern." (PMID 39553548, 2024). "In addition to GS and Bartter syndrome, uEVs is also utilized in some renal tubular disorders such as nephrogenic diabetes insipidus, and familial hyperkalemic hypertension due to KLHL3 mutation." (PMID 34179047, 2021). "Pseudohypoaldosteronism type 2 (PHA2), also known as Gordon syndrome, is a rare genetic disorder associated with variants in WNK1, WNK4, KLHL3, and CUL3." (PMID 39527282, 2025). "Pseudohypoaldosteronism type II (PHAII), also called Gordon syndrome, is a rare hereditary disease caused by variants in the WNK1, WNK4, KLHL3 and CUL3 genes." (PMID 34022862, 2021).
Gordon syndrome (10 papers, 2013 to 2023). An extremely rare multiple congenital malformation syndrome characterized by congenital contractures of hand and feet with variable degrees of severity of camptodactyly, clubfoot and, less frequently, cleft palate. "This patient is the first case of Gordon syndrome (GS) within the Chinese population caused by a heterozygous KLHL3 mutation." (PMID 32774943, 2020). "A Gordon syndrome mouse model has also been created with a Klhl3 mutation in the BTB domain, which should aid a better understanding of the Kelch-like 3/Cullin 3 interaction and contribute to possible future novel antihypertensive drug targets." (PMID 31795491, 2019). "When Gordon syndrome-causing KLHL3 mutations are examined, it is clear that they affect the binding of Kelch-like 3 with the acidic motif on WNK4-kinase in different ways." (PMID 31795491, 2019). "The phenotypic severity of Gordon syndrome varies according to different causative mutations (CUL3 > recessive KLHL3 > dominant KLHL3 > WNK4 > WNK1)." (PMID 31795491, 2019). "Most described Gordon's syndrome mutations in KLHL3 are located either close to the peptide binding site or more randomly throughout the structure with no recognizable pattern between the Kelch repeats." (PMID 24641320, 2014). "Replacement of KLHL3 Gordon's syndrome-causing mutations located within the Kelch domain (R528H or N529K) reduced binding to the WNK4 degron peptide approximately 10-fold." (PMID 24641320, 2014). "Loss-of-function mutations in either CUL3 or KLHL3 cause the hereditary high blood pressure disease Gordon's syndrome by stabilizing WNK isoforms." (PMID 24641320, 2014). "Patients with Gordon's syndrome have been identified with mutations in either of these residues and notably mutation of Arg528 to a histidine residue is the most prevalent KLHL3 mutation described thus far." (PMID 24641320, 2014). "The KLHL3 residues that are mutated in Gordon's syndrome are widely distributed across the Kelch domain of KLHL3." (PMID 24641320, 2014). "Parallel to Gordon's syndrome mutations in KLHL3, several of the reported KEAP1 mutations directly perturb the interface with NRF2, whereas others are likely to disrupt the structural integrity of the Kelch domain fold." (PMID 24641320, 2014). "We next selected 15 different dominant Gordon's syndrome mutations located in different domainsof KLHL3, generated in stable HEK-293 cell lines,and tested how each mutation affects association with CUL3 and WNK1." (PMID 23387299, 2013). "Our findings highlight that disease-causing mutationsthat disrupt KLHL3–WNK interactions lead to Gordon's syndrome." (PMID 23387299, 2013). "The findings of the present study also emphasize that the missense mutations in WNK4 thatcause Gordon's syndrome strongly inhibit interaction with KLHL3." (PMID 23387299, 2013). "The identification of mutations in CUL3 and KLHL3 in Gordon's syndrome patients suggeststhat these two proteins may also form a CRL E3 complex that regulates blood pressure." (PMID 23387299, 2013). "The finding that disease-causing mutations ofGlu562 and Gln565 markedly impair binding to KLHL3 is very exciting, as thissuggests that loss of interaction with CUL3–KLHL3 may lie at the heart of understanding howmissense mutations in these residues of WNK4 results in Gordon's syndrome." (PMID 23387299, 2013). "Lifton’s group, using whole exome sequencing, identified two further genes implicated in Gordon syndrome, KLHL3 (5q31), which encodes Kelch-like 3 (PHA2D), which was also identified by a French group, and CUL3 (2q36), which encodes Cullin 3 (PHA2E)." (PMID 31795491, 2019). "More recently, mutations in two further genes have been identified, KLHL3 and CUL3, which account for 80% of families with Gordon syndrome." (PMID 31795491, 2019). "For instance, dopatients with KLHL3 A340V and A494T Gordon's syndrome have the same CUL3/KLHL3/WNK/SPAK/NCC pathwayabnormalities as those with KLHL3 L387P?" (PMID 24266877, 2014).
Gordon syndrome (continued). "Although mutations of Cul3, KLHL3, and WNKs are known as the cause of Gordon syndrome, the NCX–CaN–NCC regulation system is independent of the Cul3–KLHL3–WNK regulation cascade." (PMID 32603346, 2020). "Since the recognition of this predominantly autosomal dominant condition in the 1960s, the study of families with Gordon syndrome has revealed four genes WNK1, WNK4, KLHL3, and CUL3 to be implicated in its pathogenesis after a phenotype–genotype correlation was realised." (PMID 31795491, 2019). "Other Gordon's syndrome mutations in KLHL3, including Q309R and N529K, are not involved in direct contact between the two proteins, but are situated within close proximity to the peptide-binding site." (PMID 24641320, 2014). "The double glycine motif is conserved in KLHL2 and KLHL3, but there are currently no reported Gordon's syndrome mutations at these sites." (PMID 24641320, 2014). "Furthermore, it offers a structural explanation for the disruptive effects of a number of Gordon's syndrome mutations that are described in WNK4 and the Kelch domain of KLHL3." (PMID 24641320, 2014). "The KLHL3 interaction site in WNK1 is on a non-catalytic region, which is interestingly the equivalent site on WNK4, which encompasses mutated residues in Gordon syndrome patients." (PMID 31795491, 2019).
Hyperkalemia (5 papers, 2019 to 2025). An abnormally increased potassium concentration in the blood. "In our study, the two affected boys showed typical PHA2 presentation, but their 32- and 28-year-old father and mother both had the same KLHL3 mutation, respectively, but were asymptomatic and had no hyperkalemia." (PMID 36726778, 2023).
Obesity (3 papers, 2022 to 2025). Accumulation of substantial excess body fat. "Recent studies have shown that KLHL3 deficiency in mice prevents diet- and age-induced obesity and mitigates insulin resistance and NAFLD78." (PMID 37779139, 2023). "KLHL3 deficiency or overexpression of mutant KLHL3 R528H prevented age- and diet-induced obesity and related diseases, suggesting that the function of KLHL3 as a substrate adapter contributes to accelerating obesity." (PMID 36028759, 2022). "Our results provide evidence of the extrarenal role of KLHL3, which is linked to the development of obesity and obesity-related diseases induced by diet and/or aging." (PMID 36028759, 2022). "Here, we demonstrated that KLHL3 deficiency in mice prevented diet- and age-induced obesity and mitigated IR and NAFLD." (PMID 36028759, 2022). "KLHL3 deficiency inhibited obesity, IR, and NAFLD by increasing energy expenditure with augmentation of O2 consumption and CO2 production." (PMID 36028759, 2022). "KLHL3 dysfunction caused by genetic mutations increased energy expenditure in mice, contributing to anti-obesity effects." (PMID 36028759, 2022). "Delivering dominant-negative (DN) Klhl3 using adeno-associated virus into mice, thereby dominantly expressing DN-KLHL3 in the liver, ameliorated diet-induced obesity, IR, and NAFLD." (PMID 36028759, 2022). "KLHL3 mutations in humans cause Gordon’s hypertension syndrome; however, the role of KLHL3 in obesity was previously unknown." (PMID 36028759, 2022). "The present findings demonstrate a novel function of KLHL3 mutation in extrarenal tissues, such as the liver, and may provide a therapeutic target against obesity and obesity-related diseases." (PMID 36028759, 2022). "In addition to diet-induced obesity, KLHL3 deficiency in mice fed a normal chow (NC) diet gradually mitigated body weight gain from 4 to 10 months old." (PMID 36028759, 2022). "In conclusion, Klhl3−/− mice displayed protective phenotypes that mitigated diet- and age-induced obesity, preventing IR and NAFLD progression." (PMID 36028759, 2022). "DEXA analysis showed that increased fat mass loss (19.27 vs. 10.80 g) was responsible for reducing HF diet-induced obesity in Klhl3−/− mice." (PMID 36028759, 2022). "Delivering dominant-negative (DN) Klhl3 to mice using adeno-associated virus (AAV), dominantly expressing DN-KLHL3 in the liver, ameliorated diet-induced obesity, IR, and NAFLD." (PMID 36028759, 2022). "In this study, we examined the role of KLHL3 in obesity, IR, and NAFLD using a mouse model." (PMID 36028759, 2022). "KLHL3 promotes substrate ubiquitination through interaction with CUL3-based E3 ligases, and WNK kinases are well-known substrates for KLHL3;13,14,17 however, the role of KLHL3 interactions with other substrates in obesity is unknown." (PMID 36028759, 2022). "However, evidence of the extrarenal functions of KLHL3, especially the regulation of obesity and obesity-related diseases, is limited." (PMID 36028759, 2022). "The results suggest that drugs able to regulate the production or activity of KLHL3 might offer a new approach to treating obesity." (PMID 36028759, 2022). "Diet- and age-induced obesity in control mice produced IR and NAFLD pathophysiology, but these parameters were notably alleviated in Klhl3−/− mice." (PMID 36028759, 2022). "Here, we demonstrated that lack of Kelch-like protein 3 (KLHL3) mitigated the development of obesity, IR, and NAFLD by increasing energy expenditure." (PMID 36028759, 2022). "However, the lack of KLHL3 in mice revealed increased energy expenditure in both HF diet- and age-induced obesity conditions." (PMID 36028759, 2022). "Next, we investigated whether the lack of KLHL3 in mice could modulate HF diet-induced obesity, IR, and NAFLD." (PMID 36028759, 2022). "Next, we investigated whether the lack of KLHL3 also ameliorates age-mediated obesity in mice fed a NC diet." (PMID 36028759, 2022).
lung carcinoma (2 papers, 2022 to 2025). "To further explore the function of DEMs and KLHL3 in lung cancer, we analyze the expression of the DEMs and KLHL3 in lung cancerous tissues by using UALCAN database." (PMID 35313857, 2022). "Compared with the healthy people, in the plasma of lung cancer patients, only the expression of KLHL3 was continuously downregulated, while NEDD4 and UBAC1 were increased." (PMID 35313857, 2022). "Subsequently, we explored the prognostic value of the DEMs and KLHL3 in lung cancer patients." (PMID 35313857, 2022). "Therefore, miR-199a-5p-KLHL3 may be a potential regulatory pathway in lung cancer plasma." (PMID 35313857, 2022). "KLHL3 can degrade the expression of the WNK1 protein through ubiquitination, so it may have an important role in the progression of lung cancer." (PMID 35313857, 2022). "Among the genes belonging to this family, KLHL25, KLHL3, and KLHL6 were found to be up-regulated by the fluorinated chalcone; curiously, these genes have been described to inhibit cell migration and invasiveness in lung carcinoma, diffuse large B-cell lymphoma, and chronic lymphocytic leukemia." (PMID 40332279, 2025).